CCR2 (C-C motif chemokine receptor 2)
Description:
Key functional receptor for CCL2 but can also bind CCL7, and CCL12. Also transduces signaling mediated by CCL13. Its binding with CCL2 on monocytes and macrophages mediates chemotaxis and migration induction through the activation of the PI3K cascade, the small G protein Rac and lamellipodium protrusion. Also acts as a receptor for the beta-defensin DEFB106A/DEFB106B. Regulates the expression of T-cell inflammatory cytokines and T-cell differentiation, promoting the differentiation of T-cells into T-helper 17 cells (Th17) during inflammation (By similarity). Facilitates the export of mature thymocytes by enhancing directional movement of thymocytes to sphingosine-1-phosphate stimulation and up-regulation of S1P1R expression; signals through the JAK-STAT pathway to regulate FOXO1 activity leading to an increased expression of S1P1R (By similarity). Plays an important role in mediating peripheral nerve injury-induced neuropathic pain (By similarity). Increases NMDA-mediated synaptic transmission in both dopamine D1 and D2 receptor-containing neurons, which may be caused by MAPK/ERK-dependent phosphorylation of GRIN2B/NMDAR2B (By similarity). Mediates the recruitment of macrophages and monocytes to the injury site following brain injury (By similarity). (Microbial infection) Alternative coreceptor with CD4 for HIV-1 infection.
Synonyms: CC-CKR-2; CCR-2; MCP-1-R; CD192; CMKBR2; CKR2; FLJ78302; CCR2A; CCR2B; CKR2A; CKR2B; PCLUD
Tractability: Small molecule: a drug acting on it is in phase 2 or 3 trials; a structure with a bound ligand is known; a high-quality ligand is known; it belongs to a druggable protein family. Antibody: a drug acting on it is in phase 2 or 3 trials; UniProt places it where antibodies can reach, with high confidence; its Gene Ontology location is reachable by antibodies, with high confidence; UniProt predicts a signal peptide or a membrane-spanning region; the Human Protein Atlas places it where antibodies can reach. PROTAC: its protein half-life has been measured; a small molecule that binds it is known. Other modalities: a drug acting on it is in phase 2 or 3 trials.
Target class: Chemokine receptor; Peptide receptor (family A GPCR); Family A G protein-coupled receptor; CC chemokine receptor; Membrane receptor
Chemical probes: PD070151 (high quality), PD080732, PD080813, PD081133, PD081560, PD081741, PD082109, PD082197, PD082476, PD082582, PD082626, PD082660, PD082668, PD082933, PD083542, PD083568, PD083660, PD084293, PD084541, PD084846, and 4 more
Gene: Protein-coding gene on chromosome 3 (46,353,864 to 46,360,940, forward strand). Ensembl gene ENSG00000121807.
Subcellular location: Cell membrane
Subcellular location (Human Protein Atlas): Plasma membrane; Nucleoli fibrillar center
Pathways (Reactome):
Immune System: Beta defensins; Interleukin-10 signaling
Signal Transduction: Chemokine receptors bind chemokines; G alpha (i) signalling events
Gene Ontology:
Molecular function: C-C chemokine receptor activity; CCR2 chemokine receptor binding; protein binding; C-C chemokine binding; chemokine receptor activity; identical protein binding; chemokine (C-C motif) ligand 12 binding; chemokine (C-C motif) ligand 2 binding; chemokine (C-C motif) ligand 7 binding; cytokine binding; G protein-coupled receptor activity
Biological process: chemokine-mediated signaling pathway; cytokine-mediated signaling pathway; positive regulation of astrocyte chemotaxis; positive regulation of monocyte chemotaxis; blood vessel remodeling; calcium-mediated signaling; cell chemotaxis; cell surface receptor signaling pathway via JAK-STAT; cellular defense response; cellular homeostasis; chemotaxis; dendritic cell chemotaxis; immune response; inflammatory response; inflammatory response to wounding; intracellular calcium ion homeostasis; macrophage migration; monocyte extravasation; negative regulation of adenylate cyclase activity; negative regulation of angiogenesis; negative regulation of eosinophil degranulation; negative regulation of type 2 immune response; positive regulation of alpha-beta T cell proliferation; positive regulation of CD8-positive, alpha-beta T cell extravasation; positive regulation of cold-induced thermogenesis; and 23 more
Cellular component: cytoplasm; plasma membrane; dendrite; external side of plasma membrane; membrane; neuronal cell body; perikaryon; perinuclear region of cytoplasm
Genetic constraint (gnomAD): Loss-of-function variants: 3 observed, 3.28 expected, observed/expected ratio (o/e) 0.92, 90% interval 0.4 to 1.83. That is too few expected variants to judge how well the gene tolerates losing a copy. Missense variants: 408 observed, 462.56 expected, observed/expected ratio (o/e) 0.88, 90% interval 0.81 to 0.96. Synonymous variants: 183 observed, 186.64 expected, observed/expected ratio (o/e) 0.98, 90% interval 0.87 to 1.11.
Homologues: Orthologues: macaque CCR2 (97% identical), chimpanzee CCR2 (89% identical), rat Ccr2 (80% identical), mouse Ccr2 (80% identical), pig CCR2 (79% identical), dog CCR2 (78% identical), rabbit CCR5 (71% identical), tropical clawed frog ccr2 (51% identical), zebrafish si:ch211-207g17.3 (39% identical), zebrafish ccr2 (39% identical), zebrafish ccr11.1 (36% identical), zebrafish cabz01093075.1 (36% identical), and 2 more. Paralogues in human: CCR5 (72% identical), CCR1 (53% identical), CCR3 (49% identical), CCR4 (45% identical), CX3CR1 (40% identical), CCR8 (38% identical), CCRL2 (35% identical), ACKR2 (33% identical), CCR7 (33% identical), CCR9 (32% identical), CXCR3 (30% identical), CCR6 (30% identical), and 11 more.
Diseases named in the same sentence as CCR2 in open-access papers:
CCR2 is named in the same sentence as 533 diseases in open-access papers, as found by Europe PMC text mining. Sharing a sentence is not in itself a finding about the gene and the disease. The quoted sentences say what the papers report.
breast cancer (159 papers, 2010 to 2026). A primary or metastatic malignant neoplasm involving the breast. "In mouse models of breast cancer, it was demonstrated that depleting C-C chemokine receptor type 2+ (CCR2) inflammatory monocytes resulted in the loss of 96% of tumour-associated monocytes together with ~93% of TAMs." (PMID 40385641, 2025). "Collectively, these results show that WNT5A–IL-6–CCL2 are enriched in TNBC tumors that develop metastasis and that high expression of IL-6R or CCR2 is associated with breast cancer chemoresistance and recurrence." (PMID 37607007, 2023). "In this study, a “chemokine cascade” was discovered in which breast carcinoma cells activate CCR2 on metastasis associated macrophages which controls the expression of CCL3." (PMID 36982211, 2023). "The high expression of CCL2 in the plasma of breast cancer patients is confirmed by enzyme-linked immunosorbent assay (ELISA), but the low concentration of CCR2." (PMID 36403055, 2022). "Upregulated lncRNA BLACAT1 was linked with aggressive breast cancer phenotype by lncRNA BLACAT1/miR-150-5p/CCR2 (C-C chemokine receptor type 2) axis." (PMID 36685962, 2022). "The CCR2 protein is implicated in cancer progression; however, higher CCR2 mRNA level is associated with prolonged survival of breast cancer patients." (PMID 35454884, 2022). "Overall, there was little association between CCL2/CCR2 signaling proteins and breast cancer subtype." (PMID 33888841, 2021). "Recent studies have implicated a role for CCL2 and CCR2 in progression of early stage breast cancers." (PMID 33888841, 2021). "For example, CCL2/CCR2 chemokine signaling has been overactive in several cancers, including breast cancer, and has been associated with poor prognosis." (PMID 33024416, 2020). "As reported by Pollard’s group, blocking CCL2/CCR2 interaction effectively inhibited the recruitment of metastasis-associated macrophages and inhibited breast cancer metastasis." (PMID 32993785, 2020). "Here, we observed that CCR2 overexpression and CCR2 deficiency in breast cancer cells resulted in some complementary phenotypes." (PMID 31208996, 2019). "We modulated ALDH1A1 and HTRA2 expression in CCR2 deficient and breast cancer cell lines with induced or endogenous CCR2 overexpression." (PMID 31208996, 2019). "CCL2/CCR2-mediated breast cancer progression was associated with increased growth, invasion and decreased tumor cell apoptosis." (PMID 31208996, 2019). "In summary, these data indicate that increased CCL2/CCR2 signaling in SUM225 breast cancer cells promotes cell proliferation, and invasion associated with increased TWIST1 and decreased E-cadherin." (PMID 31208996, 2019). "In a mouse model of breast cancer caused by the mammary epithelial restricted expression of the Polyoma Middle T oncogene (PyMT), genetic depletion of CCR2+ monocytes reduces the number of TAMs in primary tumors." (PMID 30483271, 2018). "Because CCR2 expression has been described as a marker for inflammatory monocytes and its expression is associated with progression of human breast cancer, we analyzed the expression of CCR2." (PMID 30094958, 2018). "Use of CCL2 versus CCR2 knockout mice further revealed that deficiency in CCL2 resulted in delayed outgrowth of mammary carcinoma, while deficiency in CCR2 enhanced tumor outgrowth." (PMID 30233579, 2018). "For example, genetic loss of host CCR2 expression suppresses monocyte accumulation and enhances the effect of doxorubicin or cisplatin treatment on the relapse of mammary tumors in the PyMT mice." (PMID 26275794, 2015). "However, cessation of this CCL2/CCR2 blockade can lead to compensatory phenotype associated with increased breast cancer metastasis, for instance." (PMID 31611871, 2019). "Differences in transcriptional programs in monocytes deficient in CCR2 vs. CCL2 might explain these disparate effects of CCR2 vs. CCL2 disruption on progression of mammary carcinoma." (PMID 30233579, 2018).
breast cancer (continued). "In addition, altered responsiveness to CCL2 through polymorphism in the receptor CCR2 also affects breast cancer susceptibility." (PMID 28077158, 2017). "CCL2 and CCR4 or CCR2 have been proposed as a potential target for decreasing myeloid-derived suppressor cells (MDSCs) and tumor-associated macrophages (TAMs) recruitment in prostate cancer, breast cancer, malignant glioma, colorectal cancer, and lung carcinoma." (PMID 39046599, 2024). "High levels of TRAIL-R3 and CCR-2 expression in TEpCs identified early breast cancer patients with poor outcomes, including a higher risk of metastasis and shorter DFS, MFS, and OS and represent new independent prognostic factors that may also be suitable therapeutic targets." (PMID 28420351, 2017). "Among the upregulated genes in the peritumoral adipose tissues of obese breast cancer patients, C‐C chemokine receptor 2 (CCR2), a receptor for CCL2, was identified." (PMID 41160815, 2026). "Overall, these studies provide insight into how CCL2 and HGF function to coordinate breast cancer growth, survival, invasion, and metabolism, and demonstrate that targeting CCR2 and MET inhibit DCIS progression." (PMID 40736024, 2025). "CCL2-secreting breast cancer cells have been shown to interact with CCR2+ macrophages to facilitate their metastasis to lung and bone." (PMID 39996058, 2025). "At this time, we cannot conclude that pharmacologic inhibition of CCR2 will result in the same changes in breast cancer growth as genetic targeting of CCR2." (PMID 40736024, 2025). "CCL2 + EVs derived from metastatic breast cancer cells are more likely to be taken up by CCR2 + macrophages in lung tissues, which is consistent with our findings." (PMID 40343498, 2025). "Specifically, in breast cancer, the chemokine receptors that exhibited the most significant correlations were CCR2, CCR4, CCR5, CCR6, CCR8, CXCR2, and CX3CR1." (PMID 40649753, 2025). "In a mice model of breast cancer, it was demonstrated that cooperation of CCR2 monocytes with tumoricidal TMEM173+ neutrophils targets disseminated tumor cells in the lungs and prevents metastatic outgrowth." (PMID 40427136, 2025). "First, CCR2-KO or Merestinib treatment alone reduced the growth and survival of mammary carcinomas and inhibited M2 macrophage recruitment, indicating disruptions to CCL2 and HGF signaling with inhibition of CCR2 or MET." (PMID 40736024, 2025). "In models of breast cancer lung metastasis, the activation of macrophages expressing CCR2 by CCL2 leads to the production of CCL3, which in turn mediates TAM retention via CCR1 signaling." (PMID 39201480, 2024). "C-C Motif Chemokine Ligand (CCL) 2, a ligand for CCR2, is expressed in breast cancer tissues, promoting the activation and migration of tumor antigen-specific Tregs to tumor sites." (PMID 39000453, 2024). "As TREM2+ macrophages are infiltrating in nature during cancer development and transcriptionally proximal to CD14+ CCR2+ monocytes in breast cancer, they are concluded as HSC-derived recruited macrophages." (PMID 39104525, 2024). "Breast cancer growth and breast cancer cell stemness were suppressed through the synergistic effect of CCR2 and β-catenin inhibition." (PMID 39044824, 2024). "Previous research has found that CCR2 can exert immunosuppressive effects by interfering with the maturation of dendritic cells in breast cancer." (PMID 39015296, 2024). "Reduced interaction between CCL2 and CCR2 on breast cancer cells can hinder their migration and survival, possibly through diminished activation of Smad3 or MAPK signaling." (PMID 38360633, 2024). "Studies have linked CCR2 expression and CCL2 secretion to poor prognosis in various cancers, including breast cancer, pancreatic cancer, and prostate cancer." (PMID 39201480, 2024). "The CCL2/CCR2 axis is involved in inflammatory responses and the growth and metastasis of many tumors, including breast carcinoma and pancreatic ductal adenocarcinoma." (PMID 39376728, 2024).
breast cancer (continued). "CXCR2-associated chemokines secreted by KDM2A-expressing CAFs stimulated M2 macrophage polarization, which in turn secreted CCL2 to increase paclitaxel resistance in breast cancer cells by activating CCR2 signaling." (PMID 37821959, 2023). "Because CCL2 is recruited in Gr1-positive inflammatory monocytes in the lung, the CCL2/CCR2 axis is also responsible for organ-specific metastasis of breast cancer." (PMID 37056561, 2023). "In this study, we showed that GEM treatment promoted breast cancer lung metastasis in a spontaneous breast cancer mouse model with accumulated CCR2+ monocytes and macrophages in the lungs." (PMID 36976637, 2023). "In CCR2 knockout mice, we detected a significant decrease in brain metastasis established by breast cancer E0771-BrM and melanoma Yumm1.7-BrM cells." (PMID 37149684, 2023). "Deletion of Ccr2 increased the proportion of circulating EPCs in WT mice, and the presence of mammary tumors further increased this proportion by twofold." (PMID 37208442, 2023). "Nevertheless, TAMs in mammary tumors are mostly blood-derived and primarily originate from the recruitment and differentiation of inflammatory CCR2+Ly6ChiCX3CR1low monocytes." (PMID 37445941, 2023). "Primary tumor–derived CCL2 can enhance breast cancer metastasis assisted by the recruitment of Ly6C+CCR2+ monocytes and retention of MAMs." (PMID 36976637, 2023). "In agreement with our result, it has been reported that the knockdown of CCR2 by siRNA inhibits tumor growth in breast cancer." (PMID 37325423, 2023). "CCL2, a dominant monocyte chemoattractant protein to recruit macrophages through binding to CCR2, was found to be a key mediator for osteoclastogenesis in bone metastasis of breast cancer and prostate cancer." (PMID 35715847, 2022). "Extracellular flux analysis and biochemical assays revealed that CCL2/CCR2 signaling in breast cancer cells enhanced glycolytic enzyme expression and activity." (PMID 35405500, 2022). "The ablation of CCL8 in mice implanted with breast cancers reversed the chemoattractant effect of M2 macrophages in a CCR2-dependent manner." (PMID 36532057, 2022). "In summary, MET receptor activity is an important mechanism for CCL2/CCR2-mediated progression and metabolism of early-stage breast cancer, with important clinical implications." (PMID 35405500, 2022). "We demonstrate that CCR2 mediates breast cancer growth, invasion and glucose metabolism through MET receptor-dependent mechanisms." (PMID 35405500, 2022). "CCR2 knockdown in DCIS.com breast cancer cells inhibited the growth and invasion of breast lesions in the MIND model." (PMID 35405500, 2022). "The present research has confirmed that blocking the CCL2/CCR2 axis can prevent the growth of prostate and breast cancer cells." (PMID 36403055, 2022). "To understand how CCL2/CCR2 signaled in breast cancer cells in the context of other oncogenic receptors, we used candidate and unbiased profiling approaches." (PMID 35405500, 2022). "CCL2 binds to CCR2 on the surface of metastasis-associated macrophages, causing the macrophages to generate CCL3 and increasing breast cancer lung metastasis." (PMID 36403055, 2022). "The detection of plasma CCL2 and CCR2 combined with CA 15-1 can be used as a biomarker for breast cancer diagnosis." (PMID 36403055, 2022). "As a result, CCL2 and CCL2/CCR2 as therapeutic targets for breast cancer remain to be further investigated." (PMID 36403055, 2022). "The C-C Ligand 2 (CCL2) and its primary receptor CCR2 are key regulators of macrophage recruitment, and their expression are upregulated in prostate, glioma and breast cancers." (PMID 35405500, 2022). "CRISPR knockout and pharmacologic inhibition of MET revealed that CCL2/CCR2-induced breast cancer cell proliferation, survival, migration and glycolysis through MET-dependent mechanisms." (PMID 35405500, 2022). "Our studies demonstrated that MET is important in CCL2/CCR2-mediated breast cancer growth and invasion." (PMID 35405500, 2022).